RNU6-1312P (RNA, U6 small nuclear 1312, pseudogene)
Gene: Small nuclear RNA gene on chromosome 2 (83,657,735 to 83,657,842, forward strand). Ensembl gene ENSG00000199295.
Homologues: Orthologues: chimpanzee U6 (90% identical), macaque U6 (83% identical). Paralogues in human: RNU6-820P (81% identical), RNU6-11P (80% identical), RNU6-16P (80% identical), RNU6-37P (80% identical), RNU6-509P (80% identical), RNU6-737P (80% identical), RNU6-86P (80% identical), RNU6-1083P (79% identical), RNU6-1131P (79% identical), RNU6-12P (79% identical), RNU6-1316P (79% identical), RNU6-1323P (79% identical), and 1286 more.